Y_RNA (Y RNA )
Gene: Miscellaneous RNA gene on chromosome 18 (49,871,555 to 49,871,666, reverse strand). Ensembl gene ENSG00000201668.
Homologues: Orthologues: chimpanzee Y_RNA (98% identical), macaque Y_RNA (95% identical). Paralogues in human: Y_RNA (83% identical), Y_RNA (82% identical), RNY1P5 (81% identical), Y_RNA (81% identical), Y_RNA (80% identical), Y_RNA (79% identical), RNY1P1 (78% identical), Y_RNA (78% identical), RNY1 (77% identical), RNY1P6 (77% identical), Y_RNA (77% identical), RNY1P14 (76% identical), and 93 more.